BRCA2 (BRCA2 DNA repair associated)
Diseases named in the same sentence as BRCA2 in open-access papers (continued):
Sharing a sentence is not in itself a finding about the gene and the disease.
prostate carcinoma (514 papers, 1998 to 2026). A carcinoma that arises from epithelial cells of the prostate gland. "BRCA2 pathogenic variants increase the risk of prostate cancer development by 3- to 8.5-fold and are associated with aggressiveness and high mortality, prompting early screening for BRCA2 carriers." (PMID 41423785, 2026). "While SIADH and TMA have been individually reported in prostate cancer, their sequential occurrence in a BRCA2-mutated setting is unique." (PMID 41669591, 2026). "In prostate cancer, the combination of BRCA2 and APC mutations was one of the most notable associations." (PMID 41395625, 2025). "Men with BRCA2 mutations, in particular, have a significantly elevated risk of developing prostate cancer, often at a younger age and with more aggressive forms of the disease." (PMID 40852019, 2025). "Prostate cancer screening in men with LP/P BRCA2 variants is recommended, predominantly based on a single study with a PSA threshold for biopsy of 3 ng/ml." (PMID 39838196, 2025). "BRCA2 Mutation: Men who carry a BRCA2 mutation have a threefold increased risk of developing prostate cancer compared to the general population." (PMID 41541272, 2025). "For example, breast cancer susceptibility gene 1 (BRCA1) and breast cancer susceptibility gene 2 (BRCA2) have been shown to be closely associated with prostate cancer aggressiveness and patient prognosis." (PMID 39917165, 2025). "Prostate cancers showed high rates of BRCA2 and APC co-mutations, indicating potential benefit from combined PARP and Wnt-targeted therapies." (PMID 41395625, 2025). "Our findings suggest that specific genetic mutations, including PIK3CA, LRP6, LRRK2, and BRCA2, are linked to prostate cancer metastasis and BCR." (PMID 40660132, 2025). "Genes associated with prostate cancer at exome‐wide significance include BRCA2, a known risk factor, as well as other breast‐cancer risk genes CHEK2 and ATM for which previous evidence has been more equivocal." (PMID 39749474, 2025). "In the case of acquired resistance, reversion mutations in BRCA1 or BRCA2 that restore HR proficiency are found in 50% or more of patients, including prostate cancer." (PMID 40460119, 2025). "In line with previous research, we demonstrated that both men with LP/P BRCA1 and BRCA2 variants are at a high risk of prostate cancer diagnosis, with the highest risk among men carrying LP/P variants in BRCA2." (PMID 39838196, 2025). "In contrast to established prostate cancer cell lines, this approach provides the flexibility to model Brca2 loss in primary cells together with co-occurring genomic alterations commonly seen in BRCA2-mutant human CRPC." (PMID 40460119, 2025). "For instance, poly(ADP)-ribose polymerase inhibitors target DNA repair defective prostate cancer (especially BRCA2 and PALB2 biallelic loss)." (PMID 40685286, 2025). "Risk factors for prostate cancer include age, black race, a history of prostate cancer in the immediate family (brother, father), BRCA2 mutations and Lynch syndrome." (PMID 40364098, 2025). "The prostate cancer risk (43% by age 80) is also strikingly high and comparable to that for BRCA2 PTV carriers." (PMID 40451289, 2025). "HRD prevalence in colorectal (10–15%), pancreatic (15–20%), NSCLC (5–10%), and prostate (20–25%) cancers suggests therapeutic potential, with trials like TRITON2 showing olaparib PFS of 8.1 months in BRCA2-mutated prostate cancer." (PMID 40864792, 2025). "This similar SIR implies a surveillance bias, but an increased risk of poorly differentiated prostate cancer and prostate cancer-specific death in BRCA2, 999del5 (c.771_775del) carriers indicates an underlying biological explanation." (PMID 39838196, 2025). "The etiology of prostate cancer remains incompletely understood, but established risk factors include advancing age, race and ethnicity, genetic mutations (such as BRCA1 and BRCA2), Lynch syndrome, and a family history of prostate cancer." (PMID 40493591, 2025).
prostate carcinoma (continued). "Overall, these data suggest a clear relationship between BRCA2 mutation carrier status and prostate cancer risk, as well as genetic variants in HOXB13 and localized prostate carcinoma." (PMID 40433050, 2025). "Previous studies have already established a link between mutations in BRCA2 and vulnerability to prostate cancer." (PMID 40433050, 2025). "Germline BRCA2 pathogenic variants (PVs) are known to cause ~4% of prostate cancer, but other homologous repair genes, BRCA1, ATM, PALB2 and Lynch syndrome genes are also involved." (PMID 40046829, 2025). "Men harboring pathogenic BRCA2 variants are now advised to initiate prostate cancer screening, prostate-specific antigen (PSA) and digital rectal examination, at younger ages, given elevated risk and the propensity for aggressive tumors." (PMID 41440226, 2025). "BRCA2 mutations contribute to a 2–6 fold relative risk for prostate cancer and have been identified in approximately 5–13% of metastatic prostate cancer patients." (PMID 40660132, 2025). "Such a conclusion lends additional support to the assertion that mutations of BRCA2 cause a pre-disposition to prostate cancer, perhaps due to impaired DNA repair function." (PMID 40433050, 2025). "Similar results were demonstrated in our study where we found the BRCA2 mutation in 26 of 66 prostate cancer patients while only four carry this mutation in control group." (PMID 40433050, 2025). "Men with BRCA2-mutated or ATM-mutated prostate cancer have an increased risk of developing aggressive disease and show relatively poor prognosis." (PMID 40046829, 2025). "In BRCA2-deficient cells, including prostate cancer, WRN is preferentially localized on the replication fork." (PMID 40649870, 2025). "Genotyping of the HOXB13 and BRCA2 genes in both prostate cancer cases and controls identified significant associations between specific alleles of these genes and prostate cancer." (PMID 40433050, 2025). "Prostate cancer patients with BRCA2 mutations often respond better to platinum-based chemotherapy like carboplatin, since their tumors are more vulnerable to DNA repair–targeting drugs." (PMID 41541272, 2025). "In total, PV/LPVs were detected in 11% of individuals across eight genes linked to prostate cancer, most frequently in BRCA2 (3.98%)." (PMID 40638876, 2025). "breast cancer gene 1 (BRCA1) and breast cancer gene 2 (BRCA2) are key genes in HR, and their mutations are associated with aggressive prostate cancer (PCa)." (PMID 41236806, 2025). "Here, we report the case of a patient with germline BRCA2-mutated prostate cancer treated with a PARPi." (PMID 38355834, 2024). "Here we report a case of prostatitis carcinoma with a mutation in the BRCA2 gene in a patient who underwent robotic-assisted radical prostatectomy for prostatitis carcinoma after medication was not effective." (PMID 39364320, 2024). "BRCA2 germline mutations are known to predispose carriers to various cancer types, including breast, ovarian, pancreatic and prostate cancer." (PMID 39702187, 2024). "Men with a family history of prostate cancer (inherited risk factors), genetic risk factors (germline mutations—BRCA2 gene), and specific race (African ancestry) have an elevated risk for developing prostate cancer." (PMID 39456593, 2024). "BRCA gene mutations (especially BRCA1 and BRCA2 genes) are primarily involved in breast and gynecological cancers but are also a risk factor for pancreatic or prostate cancers." (PMID 39594177, 2024). "BRCA2 is the most frequently mutated DNA damage repair factor in prostate cancer patients, with a high mutation rate of 12.7% in advanced prostate cancer patients." (PMID 37934606, 2024). "Here we report the results of extensive genomic interrogation of a BRCA2-mutant prostate cancer patient with acquired resistance to PARPi combination therapy mediated by multiple BRCA2 reversion mutations." (PMID 38355834, 2024).
prostate carcinoma (continued). "It is estimated that BRCA2 mutations account for approximately 5% of familial prostate cancer cases." (PMID 39364320, 2024). "Germline BRCA2 mutations have been associated with a higher risk of prostate cancer, increased mortality, and earlier age of diagnosis." (PMID 39132508, 2024). "BRCA2 is the most frequently mutated gene among the DNA-repair system in subjects with prostate cancer, with a frequency of somatic alterations of 8–12%, of which the germline is 5.3%." (PMID 39335746, 2024). "The results showed that the average mRNA levels of AURKB in BRCA2-deficient patient samples were significantly lower than those in BRCA2-proficient patient samples, especially in BRCA2-deficient prostate cancer patient samples." (PMID 37934606, 2024). "Mutations in the BRCA2 tumor suppressor gene have been associated with an increased risk of developing prostate cancer." (PMID 37934606, 2024). "Pathogenic variants in BRCA2 also increase risk of prostate cancer and male breast cancer, with male pre-symptomatic carriers typically being offered prostate-specific antigen screening in the NHS." (PMID 39438716, 2024). "Integrative clinical genomics of advanced prostate cancer revealed that >10% of metastatic castration-resistant prostate cancers (mCRPCs) exhibit biallelic loss of BRCA2 42, and Olaparib has been approved to treat BRCA-mutant mCRPC6." (PMID 38580648, 2024). "Other unlisted high-scoring genes, such as BRCA1 and BRCA2, have been confirmed to be involved in DNA repair and are also linked to prostate cancer." (PMID 38530778, 2024). "It is noteworthy that cases of prostate cancer in patients with BRCA2 mutations are rare in clinical practice." (PMID 39364320, 2024). "For prostate cancer subtypes, the most frequently mutated genes are BRCA2/FANCD1 at 54.5% and FANCA at 12%, both in prostate small cell carcinoma." (PMID 39421870, 2024). "BRCA2 mutations have been linked to an increased risk of prostate cancer, particularly in patients diagnosed with early-onset disease." (PMID 39364320, 2024). "Several inherited mutations (e.g., BRCA1 and BRCA2) are associated with varying degrees of increased predisposition to prostate cancer." (PMID 37202470, 2024). "Co-deletion of RB1 and RNASEH2B was associated with PARPi resistance in prostate cancer cell lines due in part to E2F1-induced BRCA2 expression, however, inhibition of ATR was able to overcome this resistance via disruption of E2F1-induced BRCA2 expression." (PMID 37430137, 2023). "Background and aims: International guidelines recommend testing BRCA2 in men with prostate cancer, due to the presence of a strong association with this gene." (PMID 36612302, 2023). "The presence of a pathogenic or deleterious mutations in BRCA1 or BRCA2 is associated with a greater risk of developing breast, ovarian, pancreatic, and prostate cancers but are also predictive to response to olaparib." (PMID 37907567, 2023). "BRCA2 appeared to be the most common HRR mutation in prostate cancer with a prevalence of approximately 5%." (PMID 36980735, 2023). "BRCA1 increases the risk of prostate cancer in patients less than 65 years old by 1.8 fold and BRCA2 by 4.5 times." (PMID 36998466, 2023). "Screening is recommended for people with a family history of prostate cancers, African Americans, and those with documented germline mutations in the BRCA2 gene, starting at 40–45 years of age, depending on each guideline." (PMID 37021836, 2023). "It has also been reported that 24.5% of men with a BRCA2 germline pathogenic variant develop prostate cancer by the age of 85." (PMID 37174127, 2023). "Mutations in the BRCA2 gene predispose to breast, ovarian, and prostate cancer, but they have also been associated with ocular or cutaneous melanoma and gastric, pancreatic, gallbladder, and bile duct cancer." (PMID 37958970, 2023).
prostate carcinoma (continued). "With respect to cancer therapy, PARP inhibitors are effective treatments for ovarian, breast, pancreatic, and prostate cancers with mutations in BRCA1 or BRCA2." (PMID 37492888, 2023). "Olaparib (Lynparza®) is the first drug based on gene mutations, especially BRCA1 and BRCA2 pathogenic mutations, for the treatment of advanced prostate cancer and was highly expected to mark the dawn of personalized medicine in this field." (PMID 37174127, 2023). "Hereof, mutations in BRCA2 stand as the most prevalent germline alteration in prostate cancer and increase the risk of cancer development by as much as five-fold." (PMID 38067216, 2023). "For BRCA2 patients, there is evidence of increased risk of pancreatic cancer, prostate cancer, and melanoma." (PMID 38067403, 2023). "Regarding BRCA1 affected by compound 6, it has been seen that BRCA1 and BRCA2 pathogenic variants are associated with prostate cancer risk." (PMID 37511023, 2023). "Patients must have confirmation of a PV in the BRCA1/BRCA2 prostate cancer susceptibility genes (germline or somatic) before initiating treatment with olaparib." (PMID 37240284, 2023). "Mutations in BRCA1 and BRCA2 are known to be associated with an increased risk of prostate cancer in men." (PMID 36998466, 2023). "Recent genomic analytical advancements have revealed that BRCA1/BRCA2 pathogenic variants are the most frequent mutations among DDR genes in prostate cancer." (PMID 37174127, 2023). "A BRCA2 mutation increases the chance of developing cancer and has been linked to several diseases, including hereditary breast, ovarian, pancreatic, and prostate cancers." (PMID 37868454, 2023). "Of the inherited prostate cancers, approximately 5.3% contain BRCA2 and 0.9% contain BRCA1 mutations making these subsets of prostate cancer ideal targets for PARP inhibitor therapy." (PMID 37035242, 2023). "For men, BRCA1/2 mutation carriers face a higher risk of developing BC in comparison to the general population, while BRCA2 mutation carriers have an increased risk of developing prostate cancer." (PMID 38203374, 2023). "Male carriers of a BRCA2 gene mutation have a significantly increased risk of developing prostate cancer." (PMID 36902416, 2023). "As a result of a three-year screening, patients with a BRCA2 pathogenic variant had a higher incidence of prostate cancer, a higher proportion of clinically significant cancers, and a lower age of onset." (PMID 37174127, 2023). "In particular, prostate cancer patients with a BRCA2 pathogenic variant who were on active surveillance were 2.74 times more likely to have an upgraded Gleason score." (PMID 37174127, 2023). "In an analysis of germline mutations in Japan, 1.1% of prostate cancer cases were found to have BRCA2 pathogenic variants (0.2% in the control group)." (PMID 37174127, 2023). "Germline mutations in BRCA, especially the BRCA2 gene, are a well-known genetic risk factor for developing malignant prostate tumors." (PMID 37021836, 2023). "BRCA2 mutations confer an increased risk for several other cancer types, including pancreatic and prostate cancer." (PMID 35734584, 2022). "To test this, we extracted gene expression levels for 65 proteins that were proximal to PARP1 and present at stressed replication forks, from breast, ovarian, and prostate cancer samples with wild-type or mutated BRCA1 or BRCA2 from the cBioPortal." (PMID 36350633, 2022). "The medical consequences of a pathogenic germline variant for prostate cancer patients are mainly limited to patients with metastatic castration-resistant prostate cancer who carry a pathogenic variant in the BRCA1 or BRCA2 gene." (PMID 36581909, 2022). "Work from our group and others has shown that BRCA2 loss is sufficient to confer PARP inhibitor sensitivity in prostate cancer preclinical models." (PMID 35768576, 2022).
prostate carcinoma (continued). "Intraductal carcinoma of the prostate (IDCP) occurs more commonly in tumors that harbor a germline BRCA2 mutation than in sporadic prostate cancers, and likewise confers a higher risk of mortality." (PMID 35715489, 2022). "Male family members with a pathogenic germline variant in the BRCA2 gene have an increased risk of developing prostate cancer, for which periodic PSA screening is advised." (PMID 36581909, 2022). "BRCA2 mutations are known to be associated with a higher prostate cancer mortality, likely due to the direct involvement of BRCA2 in the homologous recombination process, as it mediates the recruitment of RAD51 to DNA double-strand breaks." (PMID 35740343, 2022). "BRCA2 reversion mutations confer resistance to olaparib and talazoparib in prostate cancer patients." (PMID 35785170, 2022). "Deleterious mutations of BRCA1 and BRCA2 are associated with increased risk of prostate cancer and experienced very aggressive course of the disease." (PMID 35785170, 2022). "Studies specific to prostate cancer have described BRCA2 mutation reversion after PARPi treatment, resulting in HRR restoration as a putative mechanism of treatment resistance." (PMID 36497408, 2022). "The frequencies of mutations in ATM and BRCA1 and BRCA2 were compared in 313 men who died of prostate cancer and 486 men with localized prostate cancer." (PMID 35732815, 2022). "The current study attempts to elucidate the molecular mechanism of differential response to PARP inhibitors in men with advanced prostate cancer harboring BRCA1 versus BRCA2 mutation." (PMID 36185208, 2022). "The best-documented mechanism of resistance in prostate cancer is acquired BRCA2 reversion mutations, where previously BRCA2-deficient tumor cells can achieve BRCA2 proficiency due to constant selective pressure of PARP inhibition." (PMID 35508696, 2022). "PARP inhibitors are actually approved in breast, ovarian, pancreatic and prostate cancers harbouring a pathogenic or likely pathogenic variant in BRCA1 or BRCA2 (BRCA1/2)." (PMID 35681784, 2022). "It is estimated that BRCA1 mutations increase prostate cancer risk by 1.8 to 3.5 times and BRCA2 by 4.6 to 8.6 times." (PMID 36294924, 2022). "BRCA1 and BRCA2 pathogenic variants (PVs) are associated with prostate cancer (PCa) risk, but a wide range of relative risks (RRs) has been reported." (PMID 34963702, 2022). "BRCA2 mutations have been identified in men with high-grade, aggressive prostate cancer, and ACA coverage of prostate cancer screening has led to an observed 3% increase in screening among men, less than 138% of the FPL in early expansion states." (PMID 35742117, 2022). "BRCA1 and BRCA2 mutations are associated with an increased risk of developing numerous cancers, including breast, ovarian, pancreatic, melanoma and prostate cancer." (PMID 35303741, 2022). "Genetic alterations of DNA repair genes, particularly BRCA2 in patients with prostate cancer, are associated with aggressive behavior of the disease." (PMID 36362213, 2022). "PARP inhibitors (PARPi) are currently indicated for the treatment of ovarian, breast, pancreatic, and prostate cancers harboring mutations in the tumor suppressor genes BRCA1 or BRCA2." (PMID 36969741, 2022). "For BRCA1 and BRCA2, breast and pancreatic cancer showed a ratio of 2:1 for germline versus somatic mutations; in ovarian and prostate cancer the ratio was 1:1, while in bladder and lung cancer, mutations were mostly of somatic origin." (PMID 34979999, 2022). "Apart from the EOC, mutations in the DDR genes, such as BRCA1 and BRCA2, are common in prostate cancer as well." (PMID 36010882, 2022). "Carriers of a pathogenic germline variant (PV) in BRCA1 or BRCA2 are at increased risk for a number of malignancies, including breast, ovarian, pancreatic, and prostate cancer." (PMID 36497436, 2022).